APOA1 (apolipoprotein A1)
Diseases named in the same sentence as APOA1 in open-access papers (continued):
Sharing a sentence is not in itself a finding about the gene and the disease.
atherosclerosis (continued). "MiR-144 binds to the 3'UTR region site of ABCA1/G1.This will reduce the outflow of cholesterol to apolipoprotein A1 (ApoA1) mediated by the ABCA1/G1 of hepatocytes and macrophages, promoting inflammatory activation and atherosclerosis." (PMID 37189131, 2023). "High-density lipoprotein (HDL) and apolipoprotein A1 (apoA1), a major component of HDL, play important roles in cholesterol efflux from macrophages, which is the first step in RCT: inhibiting atherosclerosis." (PMID 36830597, 2023). "ApoA1 is a target of oxidation, and its alteration affects RCT and contributes to atherosclerosis development." (PMID 36219354, 2023). "Here we demonstrate that superoxide radical, widely produced in early atherosclerosis, directly oxidizes HDL, and as a consequence, ApoA1 undergoes structural alterations impairing its anti-atherosclerotic functions." (PMID 36219354, 2023). "Apolipoprotein A-I (APOA1) is a multifunctional lipoprotein and has therapeutic potential in several diseases, such as atherosclerosis, thrombosis, diabetes, cancer or neurological disorders." (PMID 36077467, 2022). "In order to evaluate the effect of the two apoA1 isoforms on regression, we used the diet switch plus MTP inhibitor model as a simple method to ameliorate the hypercholesterolemia in atherosclerosis prone mice." (PMID 35120132, 2022). "As such, in contrast to our original hypothesis, we anticipate that changes in the bone marrow functionality do not play a significant role in the increased atherosclerosis susceptibility detected in HDL deficient human APOA1 mutation carriers and APOA1×LDL receptor DKO mice." (PMID 34698355, 2022). "APOA1, the main protein of high-density lipoprotein (HDL) which shows protective effects on atherosclerosis, was increased when cGAS was inhibited." (PMID 33589571, 2021). "Altogether this indicates that the apoB/apoA-1 ratio, reflecting the balance between atherogenic and anti-atherogenic particles, is a useful risk indicator for coronary heart disease and the development of atherosclerosis, in a similar manner as LDL-C and non-HDL-C or apoB only." (PMID 34851955, 2021). "The general scientific perspective considers HDL-C and its principal constituent Apolipoprotein A1 as inversely related to CVD and atherosclerosis development." (PMID 34066182, 2021). "Among them, ANXA2, ApoA1, PGK1, CEBPB and MAP3K3 were related to atherosclerosis and cerebral inflammation." (PMID 34295249, 2021). "Consequently, increasing APOA1 synthesis may become a new approach for treating atherosclerosis." (PMID 32566106, 2020). "A large number of preclinical studies support epidemiological data from animal models of atherosclerosis, which suggest that HDL/apoA-1 intervention reduces plaque size and inflammation." (PMID 32178685, 2020). "Human and recombinant APOA1 have been reported to promote HDL-mediated cholesterol efflux and improve atherosclerosis." (PMID 33456482, 2020). "Three proteins, including PON1, APOA1, and GPD2, involved in atherosclerosis, cardiovascular disease, and lipid metabolism, were selected for validation via western blotting." (PMID 32566106, 2020). "Apolipoprotein-A1 (Apo-A1), which is the major apolipoprotein of high-density lipoprotein (HDL), seems to confer a major protection role against atherosclerosis development in the human body." (PMID 32626555, 2020). "Despite the beneficial effects ApoA1 appears to illicit in regression of disease, there have been studies to show the opposite with HDL retarding the progression of atherosclerosis." (PMID 29986413, 2018).
atherosclerosis (continued). "The effect of overexpressing proteins involved in HDL biogenesis, especially apoA-1 and ABCA1, on the development of atherosclerosis has been the subject of several investigations." (PMID 28278274, 2017). "Apolipoprotein A1 (ApoA1) has been shown to have anti-inflammatory properties and to reduce atherosclerosis; one would expect, therefore, that farmers (who are at lower risk for cardiovascular disease than the general population) had higher (rather than lower) apoA1 than referents." (PMID 27160764, 2016). "IgG anti-apolipoprotein A-1 (IgG anti-apoA-1) antibodies are present in patients with systemic lupus erythematosus (SLE) and may link inflammatory disease activity and the increased risk of developing atherosclerosis and cardiovascular disease (CVD) in these patients." (PMID 25890187, 2015). "Apolipoprotein A1 is the main protein of HDL particles and its levels are decreased in atherosclerosis." (PMID 26074960, 2015). "Apolipoprotein A1 (APOA1) is the major protein component of HDL in plasma and is believed to have a protective effect against atherosclerosis by participating in the reverse transport of hepatic cholesterol from tissues to the bile for excretion." (PMID 22682430, 2012). "ApoA-1 is the primary protein component of HDL-c, well-known for its roles in regulating cholesterol transport, modulating inflammation and immune responses, and preventing atherosclerosis." (PMID 40951435, 2025). "In brief, the variation of the ApoB/ApoA1 ratio arising from the progress of CHB disease is worth studying, and it can indirectly suggest the effect exerted by the progress of CHB disease on atherosclerosis, and add novel insights for the early diagnosis of LC and HCC." (PMID 38744926, 2024). "ApoA1 is the main component of HDL-C, which also showed a clear correlation with atherosclerosis." (PMID 38459364, 2024). "Furthermore, this work delineates, for the first time, an intimate relationship between anti-apoA1 IgG and kynurenine pathway activation, whose pathophysiological relevance is broad and covers HIV, autoimmunity, and atherosclerosis pathogenesis." (PMID 38414919, 2024). "Although APOA1 contributes to the formation of classical HDL particles and contributes to the protection from atherosclerosis, more recent data show that the anti-inflammatory and antioxidant properties of HDL are greatly affected by its overall apolipoprotein content." (PMID 37375802, 2023). "After 40 weeks, the mice treated with rAAV8 apoA1 Milano demonstrated a substantial reduction of atherosclerosis, while there was no such positive effect in mice treated with empty rAAV8, and they were sacrificed before the experiment had started." (PMID 36979690, 2023). "Under oxidation, ApoA1 loses its ability to mediate cholesterol efflux from cells, RCT becomes compromised, the cholesterol accumulates in the sub-intima cells of the vessel wall and triggers the atherosclerosis process." (PMID 36219354, 2023). "Indeed, in hyperlipidemic mouse atherosclerosis studies, overexpression of transgenic human apoA1 led to increases in HDL-C and RCT and decreases in the extent of atherosclerosis." (PMID 35052806, 2022). "Apolipoprotein A1 (apoA1), the major protein constituent of high-density lipoproteins (HDL), has been previously considered as a potential treatment target for restenosis and as a modulator of atherosclerosis progression." (PMID 35361857, 2022). "A large number of studies have demonstrated that DKD and H. pylori infection may contribute to dyslipidemia by affecting ApoA1, ApoB, TG, TC, HDL, LDL, and oxidized LDL levels, and that these effects may promote the development of atherosclerosis." (PMID 29849820, 2018).
atherosclerosis (continued). "For example, in contrast to Apoe−/− mice which develop atherosclerosis at a young age, Apoa1−/− mice do not develop atherosclerosis when fed normal or atherogenic diets." (PMID 30282955, 2018). "ApoA1 or high-density lipoproteins (HDL), which major apoliprotein is apoA1, has been shown to protect vascular endothelium in many pathological conditions including atherosclerosis and stroke." (PMID 24349659, 2013). "Also an increased ApoB/ApoA1 ratio has a role in clinical CVD development, including subclinical atherosclerosis." (PMID 21692678, 2011). "ApoA-1 mimetic peptides have been shown to reduce atherosclerosis and attenuate inflammation in experimental animals without significantly changing plasma lipid levels." (PMID 21345230, 2011). "The apoA-1 mimetic peptide 4F, synthesized from either D (D-4F) or L (L-4F) amino acids, promotes the ability of HDL to protect low-density lipoprotein (LDL) from oxidation in animal models of atherosclerosis." (PMID 20482780, 2010). "Apolipoprotein A-1 (apoA-1), a major component of high-density lipoproteins (HDL), plays an important role in the anti-inflammatory effects of HDL and mediates protection against atherosclerosis in animal models." (PMID 20482780, 2010). "Additional research revealed that APOA1 mimetic peptides might enhance cholesterol efflux, reduce lipoprotein oxidation, and promote the formation of pre-β HDL particles, making them a promising novel therapeutic strategy for atherosclerosis." (PMID 37375802, 2023). "However, in support of an important role for PON1, genetic deficiency of neither apoA1 nor LCAT in humans is, unlike PON1 deficiency, conspicuously associated with premature atherosclerosis." (PMID 36873390, 2023). "As CSL-112 demonstrated an ability to induce cholesterol efflux from foam cells equally in patients with and without stable atherosclerosis, it thus became a subject of assessment in a randomized controlled study of a single 6 g apoA1 injection in 17 thousand individuals with MI (AEGIS II trial)." (PMID 36979690, 2023). "Apolipoprotein A1 (ApoA1) is a crucial functional component of high-density lipoprotein (HDL) particles, which reverse cholesterol transport from peripheral tissue to the liver, and ApoA1 decreases blood cholesterol levels and prevents atherosclerosis formation." (PMID 36140721, 2022). "Levels of low-density lipoprotein (LDL), apolipoprotein B (ApoB), HDL, apolipoprotein A1 (ApoA1), and C-reactive protein (CRP) are significant biomarkers of vascular inflammation and are critical to almost all inflammatory disease processes including atherosclerosis." (PMID 33644628, 2021). "However, there was no significant increase in reduced APOA-1 levels in the atherosclerosis mice using the high or low dose of BBR in our study." (PMID 32231564, 2020). "Apolipoprotein A1 (ApoA1), the main protein component of HDL-C in the plasma has functions of protecting against atherosclerosis and cardiovascular disease, meanwhile it could also promote cellular cholesterol efflux and cholesterol transportation from peripheral tissues to the liver." (PMID 31391051, 2019). "Furthermore, few studies have shown better prediction by LDL-C, non-HDL-C, or apoB over the apoB/apoA-1 ratio for the amount of atherosclerosis based on calcium score, ultrasound measurements of the carotid and femoral artery, endothelial functions, or other CV measurements." (PMID 34851955, 2021). "Consistent with the hypothesis that a significant number of mechanisms underlying atherosclerosis and ACS without SMuRFs remains undiscovered, our study will be the first to elaborate metabolomic and inflammatory biomarkers, such as Lp(a), ApoB and ApoA1 interleukin-6 (IL-6) and suPAR." (PMID 36959584, 2023). "Also, we only investigated ApoA1, PON1 and PON3 enzymes in liver cells; we did not consider other factors that are related to atherosclerosis in the liver or in other tissues such as endothelium and blood." (PMID 29215336, 2017).
diabetes (258 papers, 2006 to 2026). "Patients with diabetes who received 240 mL of cranberry juice for 12 weeks showed lower serum glucose levels and improved levels of cardiovascular risk markers (apoB, apoA-1, and Paraoxonase-1)." (PMID 38752013, 2024). "AMI worldwide is associated with nine modifiable risk factors (ApoB/ApoA1 ratio, hypertension, diabetes, abdominal obesity, smoking, psychosocial factors, poor diet, regular alcohol consumption and lack of regular physical activity)." (PMID 38478535, 2024). "In comparison to other traditional risk factors such as smoking, arterial hypertension, and diabetes mellitus, ApoB and the ApoB/ApoA1 ratio have demonstrated strong and independent associations with the risk of acute myocardial infarction." (PMID 38393015, 2024). "On the contrary, people with tea drinking habits, higher education, sleep time >7 h/day, diabetes and higher levels of (hemoglobin, low density lipoprotein, apolipoprotein A1, and serum calcium) have a lower risk of IA rupture." (PMID 33746870, 2021). "In women the significant risk factor other than smoking was elevated ApoB/ApoA1 ratio, whilst among male cases BMI ≥ 25.0 and diabetes were associated with an increased risk." (PMID 28666478, 2017). "The mutations of Apolipoprotein A1/C3/A4/A5 gene cluster and the ApoAI-CIII-AIV gene cluster were associated with the lipid levels in type 2 diabetes mellitus and risk of coronary heart disease." (PMID 26608305, 2015). "Multiple logistic regression analysis of known predictors of CAD confirmed the independent role of smoking status (P < 0.001), diabetes (P = 0.001), obesity (P = 0.001), hyperlipidemia (P < 0.001) and ApoA1 (P < 0.001) as risk factors of CAD." (PMID 26173491, 2015). "More importantly, we found that high ApoA1/HDL-C ratio in serum was significantly associated with diabetes, and was superior to other variables, even after multiple-variable adjustments." (PMID 24093822, 2013). "ApoA1/HDL-C had a significant linear association with diabetes in both sexes and was superior to other lipid and lipoprotein variables among the general Taiwanese population." (PMID 24093822, 2013). "A cohort study is needed to determine the role of ApoA1/HDL-C in the development of diabetes, as susceptible individuals are increasingly considered as candidates for appropriate interventions." (PMID 24093822, 2013). "The increased ratio of ApoA1/HDL-C was significantly associated with diabetes in men (top tertile vs. lowest: OR 2.98; 95% CI: 1.12 - 7.92; P-trend = 0.030) and women (top tertile vs. lowest: OR 2.15; 95% CI: 1.00 - 4.59; P-trend = 0.047)." (PMID 24093822, 2013). "Single-nucleotide polymorphisms (SNPs) on the APOA1/C3/A5 gene cluster are associated with metabolic syndrome, dyslipidemia and diabetes." (PMID 23829168, 2013). "Based on a thorough review of the literature, this study is the first to demonstrate that the ratio of ApoA1/HDL-C was the primary risk factor for diabetes in both sexes." (PMID 24093822, 2013). "Future research should determine the association of apoA1 and apoB:apoA1 ratio on cardiovascular outcomes in First Nations peoples with diabetes." (PMID 21159217, 2011). "Both apoB and apoA1 were significantly associated with obesity when age, sex, diastolic blood pressure, homocysteine, diabetes, and insulin resistance were controlled for." (PMID 21159217, 2011). "Reduced circulating levels of ApoA1 have been associated with increased risk of incident diabetes as well as with cardiovascular events in large general population cohorts, although its prognostic value has not been clearly demonstrated in diabetic populations." (PMID 41180181, 2025). "Subgroup analysis among subjects with available apoB/apoA-1 ratio (n=68 435) showed an increased association with aortic stenosis among all groups with elevated glucose, with the highest association observed in those with known diabetes." (PMID 39915078, 2025).
diabetes (continued). "The triglycerides to Apolipoprotein A1 ratio (TG/APOA1) holds promise to be a more valuable index of insulin resistance for the diagnosis of metabolic dysfunction-associated fatty liver disease (MAFLD) in type 2 diabetes mellitus (T2DM)." (PMID 39764250, 2024). "In multivariable logistic regression, after adjusting for confounding factors, including duration of diabetes, HbA1c, smoking, BMI, hypertension, antidiabetic agents, and anti-lipid drugs, the ApoA1/HDL-C ratio was significantly associated with CAD in individuals with T2D." (PMID 38914982, 2024). "Low levels of ApoA1 are associated with type-2 diabetes mellitus, and the prospective population-based Rotterdam Study indicated that ApoA1 is a risk factor for type-2 diabetes mellitus." (PMID 35269541, 2022). "ApoA1 might turn to enhance risk of diabetes due to dysfunctional adiponect in prevailing among Turks (vs. this study)." (PMID 33794863, 2021). "Moreover, studies on Chinese Han population found that apoB/apoA1 was correlated with coronary heart disease risk factors such as diabetes mellitus and abnormal glucose tolerance." (PMID 32539722, 2020). "This unfavorable CVD profile is characterized by an elevated risk of dyslipidemia, high apolipoprotein B/apolipoprotein A1 ratio, hypertension, glucose intolerance, type 2 diabetes mellitus, as well as increased BMI, body fat percentage, abdominal and visceral adiposity." (PMID 30488037, 2018). "In pre-symptomatic women both smoking and an elevated ApoB/ApoA1 ratio were significantly more prevalent compared with matched controls, whereas in men smoking, BMI ≥ 25.0 and diabetes were significantly associated with increased risk of future development of RA." (PMID 28666478, 2017). "In the present study, a higher BMI was associated with increased risk for future RA, even when adjusting for smoking, ApoB/ApoA1 ratio, diabetes, hypertension and educational level, although, when stratifying for sex, the association of BMI ≥ 25.0 for future RA was restricted to men." (PMID 28666478, 2017). "High ApoA1 levels independently predicted incident type-2 diabetes among a sample of Turkish participants and the top tertile of serum ApoA1 level nearly doubled the risk for incident diabetes when compared with the low tertile." (PMID 24093822, 2013). "Whereas existing glucose-based diagnostic criteria remained unknown, an abnormal ApoA1/HDL-C in the Taiwanese population may indicate diabetes." (PMID 24093822, 2013). "Notably, we observed that ApoA1/HDL-C was independently associated with diabetes in both sexes, and the serum ApoB/LDL-C ratio was only consistently associated with the presence of diabetes in women." (PMID 24093822, 2013). "This apoA1 sex difference may partially explain the higher risk for coronary heart disease for women with diabetes than men with diabetes." (PMID 21159217, 2011). "However, it remains unclear whether the ApoA1/HDL-C ratio is linked to CVD in individuals with diabetes." (PMID 38914982, 2024). "In women, elevated ApoB/ApoA1 ratio (OR = 1.36 (1.03–1.80)) and smoking (OR = 1.82 (1.37–2.41)) were significantly associated with being pre-symptomatic for RA, whilst in men smoking (OR = 1.92 (1.26–2.92)) and diabetes (OR = 3.62 (95% CI 1.13–11.64)) were significant." (PMID 28666478, 2017). "Patients in the CRS group were older, had a higher proportion of diabetes mellitus, higher levels of TG, apo-B, and Scr, a higher ApoB/ApoA1 ratio, but lower levels of apo-A1 compared to the SHF group." (PMID 41908053, 2026). "The measurement of ApoB and ApoA1 does not require fasting samples and is standardized, making the ApoB/ApoA1 ratio a more balanced, comprehensive, and stable indicator of lipid metabolism and a predictor of cardiovascular disease and diabetes." (PMID 40463506, 2025).